NDRG1 (N-myc downstream regulated 1)
Diseases named in the same sentence as NDRG1 in open-access papers (continued):
Sharing a sentence is not in itself a finding about the gene and the disease.
breast carcinoma (continued). "Additionally, depletion of NDRG1 has been shown to reduce the invasion and migration of a specific breast cancer subpopulation." (PMID 37858101, 2023). "Moreover, another study in breast cancer cells has shown that NDRG1 silencing leads to reduction of cell proliferation rate, abnormalities in lipid metabolism such as enhancement of incorporation of fatty acids into neutral lipids and lipid droplets." (PMID 37249826, 2023). "One study has reported that EGR1 could localize to the NDRG1 proximal promotor and regulate cell proliferation and survival in breast cancer." (PMID 35982887, 2022). "NDRG1 was found as the downstream gene of WISP1 in the studies on the breast cancer cells." (PMID 36232736, 2022). "On a smaller scale, low levels of N-myc downstream regulated gene 1 (NDRG-1) protein in nerve tissues from resected early-stage breast cancer sections of paclitaxel-treated patients have been suggested as predictive of susceptibility to severe paclitaxel-induced neuropathy." (PMID 35015774, 2022). "However, previous studies revealed that the expression of NDRG1 decreased in esophageal, colorectal, and breast cancers, and was correlated with poor clinical outcomes." (PMID 35795037, 2022). "NDRG1 has been shown to drive tumor progression and brain metastasis in aggressive breast cancer." (PMID 35859293, 2022). "This suggested a potential involvement of NDRG1 in BrM progression within the breast cancer cohort." (PMID 36497221, 2022). "In vitro and in vivo data demonstrated a possible role of NDRG1 in breast cancer differentiation." (PMID 33808259, 2021). "Further investigations on how NDRG1 affects low-density lipoprotein uptake in triple-negative breast cancer may provide new therapeutic insights in the treatment of breast cancer." (PMID 32612361, 2020). "Besides, GR-mediated Sgk1 activation suppressed tumor cell apoptosis in breast carcinoma cells and NDRG1 was reported to be induced by Sgk1 to inhibit apoptosis in ESCC tumor cells." (PMID 32106831, 2020). "Previous study has shown that miR-769-3p could regulate breast cancer cell apoptosis via down-regulating NDRG1." (PMID 32936290, 2020). "NDRG1 is widely described as a metastasis suppressor in breast cancer." (PMID 33321961, 2020). "Moreover, they demonstrated that NDRG1 promotes breast cancer aggressiveness by altering lipid metabolism." (PMID 33321961, 2020). "These hypothesis-generating findings suggest that the role of NDRG1 in local failure in breast cancer patients and radiation resistance warrants further investigation." (PMID 33321961, 2020). "Paradoxically, other studies showed that NDRG1 might function as an oncogene or a prognostic biomarker in aggressive forms of breast cancer." (PMID 33321961, 2020). "NDRG1 has been reported to function as a metastasis suppressor gene, and it is downregulated in gastric cancer, prostate, pancreatic cancer and breast cancers." (PMID 31443698, 2019). "However, a previous study shows that several Akt-inhibitor-sensitive breast cancer cells showed marked NDRG1 phosphorylation despite the low or undetectable level of SGK1 protein." (PMID 30811403, 2019). "So that we might resolve questions on the link between NDRG1 expression and disease outcome, we examined large, recently established, public repositories of clinical breast cancer data." (PMID 29898756, 2018). "Thus, NDRG1 expression is essential to the maintenance of cell proliferation rates, viability, and morphology in breast cancer cells, especially in cell lines with high expression levels." (PMID 29898756, 2018). "This study defined a new function for the disease-associated protein NDRG1, and solidified its role as a negative prognostic marker in breast cancer." (PMID 29898756, 2018). "The function of NDRG1 in breast cancer lipid metabolism may represent a promising therapeutic approach in the future." (PMID 29898756, 2018).
breast carcinoma (continued). "Furthermore, breast cancer cells expressing constructs targeting EGR1 and NDRG1 displayed an increase in breast cancer cell migration." (PMID 30337371, 2018). "NDRG1 expression correlates with glycolytic metabolism and poor outcomes in breast cancer." (PMID 29898756, 2018). "We showed that high NDRG1 expression is a common feature of poor prognosis in breast cancer and that elevated expression is correlated with an aggressive metabolic gene signature and portends a high likelihood of disease recurrence and metastasis in several independent patient cohorts." (PMID 29898756, 2018). "Inhibiting MNKs increases the expression of NDRG1 protein and mRNA in breast cancer cells." (PMID 28545025, 2017). "Moreover, forced overexpression of WISP1 blocked the expression of NDRG1, a breast cancer tumor suppressor gene." (PMID 25732125, 2015). "Meanwhile, the NDRG1 gene in various poorly differentiated cancer cells was a frequent occurrence compared to normal cells, and the differentiation stage was viewed as a crucial standard in the determination of the prognosis of breast cancer." (PMID 23899187, 2013). "In summary, this study provides new evidence that aberrant methylation and NDRG1 is involved in the tumorigenesis of breast cancer, and it could be reactivated from a silenced state by methylation." (PMID 23899187, 2013). "Nevertheless, the notion that NDRG1 could be reactivated from a silenced state by methylation might be a possible mechanism for breast cancer." (PMID 23899187, 2013). "DNA methylation in the NDRG1 promoter was detected in 31.1% of primary breast cancer samples." (PMID 23899187, 2013). "Thus, the promoter methylation of NDRG1 was observed more frequently in breast cancer tissues than the corresponding normal tissues (P = 0.000)." (PMID 23899187, 2013). "Meanwhile, low expression of NDRG1 is liked to result in a poor clinical outcome in breast cancer." (PMID 23899187, 2013). "Low expression of NDRG1 is correlated with poor clinical outcome in breast cancer." (PMID 23227362, 2012). "For example, MYB and NDRG1 are related to ER+ breast cancer and TNBC, respectively." (PMID 22343619, 2012). "Additionally, NDRG1 contributes to breast cancer aggressiveness by modulating lipid metabolism." (PMID 38983911, 2024). "Notably, NDRG1 expression was increased in breast cancer cell lines that are resistant to AKT inhibitors, indicating that NDRG1 levels could be associated with responsiveness to available treatments." (PMID 38611020, 2024). "Since NDRG1 is mostly described as a tumor and metastasis suppressor gene, we hypothesized that deletion of the NDRG1 gene would affect the proliferative rate of breast cancer cell lines." (PMID 38983911, 2024). "However, overexpression of full-length NDRG1 functions as a promoter of tumor growth and metastasis in ER-, aggressive breast cancers, which is consistent with the previous work demonstrating where silencing of NDRG1 prevented tumor formation in highly aggressive TNBC." (PMID 38983911, 2024). "Moreover, Ndrg1 has also been recognized as a major regulator of lipid fate in breast cancer cells." (PMID 37370489, 2023). "Additionally, increased NDRG1 protein expression was observed in Her2-negative breast cancer, suggesting its role in both less aggressive and more aggressive behavior depending on breast cancer subtypes." (PMID 37858101, 2023). "However, NDRG1 mRNA levels were increased in MDA-MB-231 cells and decreased in HCC 1954 cells and MCF-7 cells compared with normal mammary cells, indicating that NDRG1 might play distinct roles in different breast cancer subtypes." (PMID 37842046, 2023). "However, we and others have shown NDRG1 to be a tumor promoter in aggressive breast cancer." (PMID 33321961, 2020). "In addition to its binding partners, structural features suggest two means by which NDRG1 might participate in lipid trafficking in breast cancer cells." (PMID 29898756, 2018).
breast carcinoma (continued). "Thus, we asked whether NDRG1 could be regulated by AP-1 network genes in response to progesterone-induced activation of SGK1 in a similar manner in breast cancer cells." (PMID 30337371, 2018). "Genomic expression analysis confirmed that elevated NDRG1 levels are associated with a metabolic gene expression profile that is a potent signature of aggressive disease in the most common solid tumor types, including breast cancer (f and data not shown)." (PMID 29898756, 2018). "Thus, enhanced expression of SGK1 and NDRG1 could explain better survival of breast cancer patients." (PMID 30337371, 2018). "In a study of SCID mice injected with a human bone metastatic breast cancer cell line, MDA-MB231-BoM, treatment with NDRG1-inducing agent Dp44mT prevented metastasis compared to the vehicle control." (PMID 40378957, 2025). "For example, TBX2 interacts with and requires early growth response 1 (EGR1) to inhibit the tumour suppressor genes N-myc downstream-regulated gene 1 (NDRG1) and cysteine protease inhibitor cystatin 6 (CST6) to promote breast cancer cell proliferation." (PMID 39912718, 2025). "Recently, TBX2 was also shown to repress NDRG1 and CST6 in breast cancer by recruiting a CoREST repression complex (LSD1, ZNF217 and HDAC1) to their promoters." (PMID 39912718, 2025). "NDRG1 is located on chromosome 8q24.3, near MYC, and amplification of this region is both common and prognostic in breast cancer." (PMID 38611020, 2024). "For example, in breast cancer, two TBX2 complexes have been identified: the TBX2-CoREST complex targets N-Myc Downstream Regulated 1 (NDRG1) by recruiting TBX2 to the NDRG1 promoter via Sp1 transcription factor (SP1)." (PMID 38965548, 2024). "The overexpression of NDRG1 is an indicator of poor prognosis in various tumor types including hepatocellular carcinoma, non–small cell lung cancer (NSCLC), and breast cancer (BC)." (PMID 39736699, 2024). "The investigations carried out by Schlee Villodre 9 on TMAs from 216 breast cancer patients (97 cases of TNBC) after neoadjuvant therapy showed different H-score median as cutoff value to discriminate between high and low NDRG1 expression." (PMID 36594086, 2023). "NDRG1 has been shown to be co-located with PVT1, and EXT1 on 8q24, a region that harbors amplification in breast cancer." (PMID 37249826, 2023). "We showed that the upregulation of SGK1 led to the activation of NDRG1, mediated by AP-1 network genes to inactivate AKT1, ERK1/2, and EGFR kinases, and thus, inhibit breast cancer cell invasion and migration." (PMID 37395734, 2023). "Of note, abnormal expression of NDRG1 or NDRG2 has been found in different cancer types, such as in esophageal cancer, colorectal cancer, breast cancer, prostate cancer, and hepatocellular carcinoma, and is significantly associated with poor prognosis." (PMID 35795037, 2022). "NDRG1, a particularly compelling candidate since it also showed upregulation in LTED breast cancer models, was further interrogated using METABRIC data." (PMID 33407744, 2021). "In breast cancer, SGK inhibition significantly impaired cell migration by downregulating N-myc downregulated gene 1 (NDRG1)." (PMID 33542904, 2020). "The genes included NDRG1, PVT1, and EXT1, which are co-located in cytoband 8q24, which is frequently amplified in breast cancer." (PMID 32612361, 2020). "The analysis revealed that the lipid transport related genes LAPTM4B and NDRG1 are coamplified in breast cancer patients, and identified genes potentially cooperating with LAPTM4B in breast cancer progression." (PMID 27711123, 2016). "NDRG1, a tumor suppressor gene for breast cancer, is a target of WISP1 and is repressed by WISP1 through DNA sequences within the NDRG1 promoter." (PMID 25732125, 2015). "We first studied the two luminal breast cancer cell lines, ZR-75-1 and MCF-7, and demonstrated increased NDRG1 expression when these cells were grown at 1% O2 for 24 hours." (PMID 24498060, 2014).
breast carcinoma (continued). "Furthermore, in order to prove that NDRG1 could be taken as a potential biomarker for breast cancer, the breast cancer tissues were analyzed further with MSP assay, and the relationship of the gene methylation status with clinicopathological data was determined." (PMID 23899187, 2013). "We observe in several breast cancer cells displaying high Akt activity and low SGK1 (including BT-474, CAMA-1 and T47D) that NDRG1 is still phosphorylated and that NDRG1 phosphorylation is suppressed by Akt inhibitors." (PMID 23581296, 2013). "Our findings indicate that the breast cancers most likely to be sensitive to Akt inhibitors would be those displaying high Akt, low SGK1 mRNA/protein and in which phosphorylation of NDRG1 is suppressed by Akt inhibitors." (PMID 23581296, 2013). "WalBC cells exhibited expression of known markers of basal invasive human breast cancers as well as increased KRT17, KRT 14 and KRT 19, DSP, s100A4, NDRG-1, ANXA1, TK1 and AQP3 gene expression and decreased gene expression of TIMP3, VIM and TAGLN." (PMID 18179684, 2008). "Finally, our results support the oncogenic properties of NDRG1 in TNBC and show the importance of the N-terminal region of NDRG1 in tumor initiation, growth and invasion in aggressive breast cancer." (PMID 38983911, 2024). "Our group has previously analyzed several independent cohorts of breast cancer patients and shown that NDRG1 was expressed at higher levels in tumor samples than in normal tissue and was more highly expressed in ER− tumors than in ER+ tumors." (PMID 38611020, 2024). "We further evaluated the effects of iron chelators on NDRG2, 3, and 4 expressions in breast cancer cells as these members have not been studied as extensively as NDRG1 in the context of carcinogenesis." (PMID 38983911, 2024). "Research demonstrates a negative correlation between NDRG1 expression and breast cancer metastasis and progression, suggesting its potential as a prognostic biomarker for early metastasis prediction." (PMID 38875364, 2024). "Overall, the results demonstrated that mitochondrially targeted iron chelators mitoDFX and mitoDFO are capable of inducing NDRG1 mRNA and protein levels in breast cancer cells, while only low levels were induced in non-malignant cells." (PMID 38983911, 2024). "Several studies, however, contradict each other: overexpression of NDRG1 in the mouse breast cancer model was shown to inhibit metastasis by regulating WNT pathway signaling, while downregulation of NDRG1 in MCF-7 cells can result in increased proliferation and invasiveness." (PMID 37479693, 2023). "This duality was also seen in breast cancer, with NDRG1 being reported as a metastasis suppressor and tumor promoter in estrogen-receptor (ER) positive and negative breast cancers, respectively 9,14-18." (PMID 36594086, 2023). "An analysis of tumors with the most recurrent outlier loss, ESR1, revealed concurrent upregulation of genes typically expressed in basal breast cancers, such as PROM1, KLK7, and NDRG1, suggesting a selection of a more basal-like phenotype in endocrine-resistant disease." (PMID 33407744, 2021). "NDRG1 is widely supported as a suppressor in prostate cancer, CRC and breast cancer." (PMID 34965023, 2021). "Moreover, the tumor metastasis suppressor N-myc downstream regulated gene-1 (NDRG1) repressed Wnt/β-catenin signaling through interacting with LRP6, resulting in suppression of metastatic phenotypes of mammary tumor cells." (PMID 34615853, 2021). "Moreover, NDRG1 was expressed at higher levels in stage III and IV breast cancer and in grade 3 tumors." (PMID 33321961, 2020). "Verma noted that NDRG1 could interfere with the combination between NEDD4 and its substrate in breast cancer." (PMID 31831018, 2019).
breast carcinoma (continued). "The stringent up-regulation of SGK1 in response to progesterone led to an activation of a tumor metastasis suppressor gene, NDRG1, via a set of AP-1 network genes to inactivate AKT1, ERK1/2, and EGFR kinases, impeding the invasion and migration of breast cancer cells." (PMID 30337371, 2018). "As NDRG1 is typically expressed in hypoxic microenvironments, however, it is likely that unlike most normal cells, the lipids in breast cancer cells are ultimately likely to have fates other than beta oxidation." (PMID 29898756, 2018). "Our study suggests that SGK1 up-regulates the expression of NDRG1, with no significant change in phosphorylation of NDRG1 in breast cancer cells." (PMID 30337371, 2018). "Taken together, our results suggest that the SGK1/NDRG1 axis mediates regulation of activation of kinases involved in breast cancer cell migration, independent of their hormonal receptor status." (PMID 30337371, 2018). "This pan-cancer correlation with hallmarks of metabolic adaptations underscores the link between NDRG1 and altered cancer metabolism, and the gene list is a potent prognostic signature in breast cancer and several other solid tumors (and data not shown)." (PMID 29898756, 2018). "Thus, consistent with the literature, we show that NDRG1 regulates the activation of EGFR and downstream kinases in breast cancer in response to progesterone." (PMID 30337371, 2018). "In a reciprocal approach, depletion of SGK1 in T47D and MDA-MB-231 cells led to a decrease in expression of NDRG1 with an inverse effect observed on migration and invasion of the breast cancer cells, regardless of progesterone treatment." (PMID 30337371, 2018). "The TCGA breast cancer analysis included quantification of the Thr346 phosphorylated form of NDRG1, but not the total protein, by reverse phase protein array." (PMID 29898756, 2018). "Taken together, the data suggest convergence of the dual mode of regulation at SGK1 in response to progesterone treatment, along with up-regulation of NDRG1 in multiple breast cancer cell lines independent of their PR status." (PMID 30337371, 2018). "NDRG1 has been reported to be a tumour suppressor and/or negative regulator of metastasis in various cancers, including breast cancer." (PMID 28545025, 2017). "Taken together, our results suggest that WISP1 inhibits breast cancer proliferation and invasion partly through the downregulation of NDRG1 expression, and that WISP1 regulates NDRG1 expression through DNA sequences located in the NDRG1 promoter." (PMID 25732125, 2015). "NDRG1 is a member of the NDRG gene family, and exhibited anticancer and metastasis-suppression effects in pancreatic cancer, colon cancer, cervical and ovarian cancer, prostate cancer, and breast cancer." (PMID 24872842, 2014). "We presume that due to the different methylation statuses of the NDRG1 promoters in certain regions, the responses of the NDRG1 promoters in the expression/non-expression breast cancer cell lines to its expression are different." (PMID 23899187, 2013). "Changes in the status of methylation of the NDRG1 gene have not been studied in detail in human breast cancer." (PMID 23899187, 2013). "Indeed, one of the Akt-inhibitor-resistant breast cancer cell lines we have analysed (MDA-MB-157) displays low SGK1 levels and NDRG1 phosphorylation." (PMID 23581296, 2013). "An established chelator, Dp44mT, was used as a positive control and, as expected, it markedly induced the expression of NDRG1 mRNA in breast cancer cells (MCF7, MDA-MB-231) and non-malignant fibroblasts (MRC5), even though the response was significantly higher in MCF7 cells." (PMID 38983911, 2024). "Moreover, breast cancer cells treated with mitoDFX demonstrated a significant increase in NDRG1 mRNA levels with only a mild effect seen on non-malignant MRC5 cells." (PMID 38983911, 2024). "The function of NDRG2 in breast cancer has not been studied as extensively as NDRG1." (PMID 38611020, 2024).